PHGDH (phosphoglycerate dehydrogenase)
Diseases named in the same sentence as PHGDH in open-access papers (continued):
Sharing a sentence is not in itself a finding about the gene and the disease.
tumor (continued). "It is well appreciated that the small-molecule PHGDH inhibitor, NCT-503, reduces production of glucose-derived serine and attenuates the growth of PHGDH-dependent cell lines and xenograft tumours." (PMID 34192988, 2021). "To examine the ATF-4 response, we measured the expression of the two ATF-4 targets, PHGDH and PSAT1, in DLD-1 tumours." (PMID 33446657, 2021). "The other compound we tested, the PHGDH inhibitor NCT502, shows efficacy in vivo to reduce growth of tumours overexpressing PHGDH." (PMID 31930708, 2020). "This analysis indicated that both IKBKE and PSAT1, similarly to PHGDH and PSPH, are significantly upregulated in an ER‐negative Pam50:basal subpopulation of tumours, with the highest proliferation index." (PMID 32783398, 2020). "Between the two groups, tumour tissue had significantly upregulated G6PD (p < 0.0001), unaltered 6PGD, and PHGDH and PSAT1 were significantly downregulated (p < 0.0001), versus the non-tumour tissue." (PMID 33028928, 2020). "We observed that the MEK inhibitor selumetinib inhibited tumor growth, with concurrent reduction in the expression levels of both ILF3 and PHGDH." (PMID 31772275, 2020). "PHGDH, in serine metabolism, is also involved in the sensitivity of TNBC tumor cells to chemotherapy." (PMID 32296646, 2020). "BRAFV600E mutant cells have higher PHGDH, PSAT1, PSPH, tumor SHMT1, and interstitial SHMT1 and GLDC expression than non-mutant cells." (PMID 31423225, 2019). "Although PHGDH knockdown decreases the E-cadherin expression and its decrease is an important step of EMT to facilitate tumor metastasis, in this study, PHGDH knockdown inhibits the tumor metastasis." (PMID 30744688, 2019). "The key enzyme in serine synthesis and SAM metabolism, PHGDH is a promising candidate and two PHGDH inhibitors, NCT-502 and NCT-503, have been shown to reduce tumor cell growth." (PMID 30283496, 2018). "High levels of PHGDH, PSPH, SHMT1 in tumor and PSPH in tumor stroma were correlated with high histological grading (p<0.001), ER negativity (p<0.001), PR negativity (p<0.001), and high Ki-67 LI (p<0.001)." (PMID 24979213, 2014). "The PHGDH shRNA dramatically reduced the expression levels of MMP-2 and VEGF, which are oncogenes important for tumor invasion and angiogenesis." (PMID 23229761, 2013). "The expression of three other genes was reduced 2-fold to 6-fold in tumor versus adjacent liver (p < 0.05, t test, df = 4), including a 3′ UTR insertion in SLC2A1 and intronic insertions in PHGDH and EFHD1." (PMID 23540693, 2013). "We inferred that PHGDH is a direct upstream regulator of FOXM1, and targeting PHGDH not only inhibited the aberrant metabolism of tumor cells but also depleted FOXM1 expression, thus attenuating tumor proliferation and invasion." (PMID 23229761, 2013). "The extensive body of research summarized herein reveals that PHGDH is not a universal oncoprotein but a context-dependent rheostat of tumor fitness." (PMID 41486146, 2026). "The following sections delineate both the core metabolic functions and these multifaceted non-canonical networks through which PHGDH orchestrates tumor progression and therapy resistance." (PMID 41486146, 2026). "For instance, CRC, PRMT1‐mediated methylation of metabolic enzymes like PGK1 and phosphoglycerate dehydrogenase (PHGDH) enhances glycolysis and serine synthesis, promotes the Warburg effect, and increases tumor stemness, thereby fostering a stress‐adaptive state conducive to resistance." (PMID 41256732, 2025). "Thus, using 2 independent mouse models of MBGRP3, we show that PHGDH inhibition via NCT-503 slowed tumor progression and produced an overall survival benefit in tumor-bearing mice." (PMID 39377369, 2025). "IHC analysis revealed that PHGDH, SLC1A5 and SLC38A2 are expressed in the GCs of TLSs in both normal and tumour colorectal tissues, suggesting that serine metabolism might play a critical role in GC formation." (PMID 40660426, 2025).
tumor (continued). "Previous studies have demonstrated that PHGDH knockdown following extracellular serine supplementation fails to rescue PHGDH-induced cell proliferation, implying a potential role for PHGDH in tumor progression via non-enzymatic mechanisms." (PMID 40681503, 2025). "Previous studies have shown that PHGDH supports nucleotide biosynthesis by fueling both the pentose phosphate pathway and the TCA cycle, thereby sustaining anabolic demands in proliferating tumor cells." (PMID 40761926, 2025). "Interestingly, we confirmed that also in tumor tissues from mice treated with JC19 or with the combo, a significant decrease in PHGDH expression is revealed." (PMID 40640948, 2025). "PHGDH inhibition represents a promising metabolic strategy for slowing tumor progression of MYC-amplified MBGRP3; however, combination therapies are more likely to achieve greater anti-tumor effects." (PMID 39377369, 2025). "Mechanistic investigations revealed that CXCL7 activates the CXCR2 receptor on tumor cells, triggering interferon signaling and promoting serine metabolism through STAT1-dependent transcriptional upregulation of phosphoglycerate dehydrogenase (PHGDH), the key enzyme in serine biosynthesis." (PMID 40368902, 2025). "We also observed that the activity of mTORC2, as indicated by the phosphorylation of AKT, was induced by the tumor medium but was not affected by the ablation of PHGDH." (PMID 38409249, 2024). "The positive correlation between CFL1 and PHGDH expression was found to be particularly pronounced in the tumor tissue of sorafenib nonresponders in a population of HCC patients." (PMID 38945960, 2024). "There was no obvious difference in PHGDH expression in T cells between Phgdhfl/fl and Phgdhfl/flCx3cr1-Cre tumor-bearing mice." (PMID 38409249, 2024). "Interestingly, low-PHGDH tumor cells CACO2 and RKO underwent a more pronounced increase in PHGDH levels under Ser/Gly withdrawal." (PMID 39706853, 2024). "Endothelial metabolism reprogramming against PHGDH could inhibit aberrant angiogenesis, restore vascular delivery, and thus enhance CAR-T cell infiltration into tumor." (PMID 38918817, 2024). "PHGDH is the first rate-limiting enzyme that catalyzes serine synthesis, and its high expression activates the serine synthesis pathway (SSP) and thus promotes tumour growth." (PMID 38577610, 2024). "Furthermore, it has been reported that outside of serine biosynthesis, PHGDH enhances mRNA translation by interacting with eIF4A1 and eIF4E, thereby promoting PDAC tumor growth." (PMID 38951899, 2024). "In CRC cells treated with the PHGDH inhibitor NCT-503, liver metastasis, and primary tumor growth were suppressed, and NCT-503 treatment reduced tumor cell migration, indicating the important role of PHGDH in tumor metastasis." (PMID 38945960, 2024). "Moreover, immunohistochemical (IHC) staining revealed that tumor tissues with FBXO7 KD exhibited increased levels of PRMT1 protein and PHGDH R236 methylation, which was largely restored by PRMT1 KD." (PMID 38839752, 2024). "We suggest that excessive PHGDH in UCEC patients may trigger competition between T cells and tumor cells in the tumor microenvironment, depleting T cells and thus suppressing the antitumor immune response." (PMID 36803157, 2023). "In estrogen receptor-negative breast cancer patients, overexpression of PHGDH leads to poor prognosis, elevated tumor grade, and high expression of proliferation markers and Ki-67." (PMID 36803157, 2023). "Moreover, PDAC tumors with augmented levels of PHGDH show attenuated NGF, tumor innervation, and shorter overall survival." (PMID 36834677, 2023). "Linc01564 increases PHGDH expression through sequestering miR-107/103a-3p, hence activating serine synthesis pathway to support HCC cell survival and proliferation in vitro and xenograft tumor growth in vivo." (PMID 35842651, 2022).
tumor (continued). "However, high expression of PHGDH, PSAT1, and PSPH is ubiquitous in tumor cells, which activates endogenous serine metabolism and thus weakens the effect of serine starvation on tumor treatment." (PMID 36699468, 2022). "Experiments show that a combination of PHGDH inhibitor (PHGDHi) and medium lacking serine and glycine (-SG) impedes tumor growth by inhibiting DNA, purine and GSH synthesis." (PMID 36699468, 2022). "Moreover, PDAC tumors with augmented levels of PHGDH typically have attenuated NGF, tumor innervation, and shorter OS, which is also consistent with other results." (PMID 36582785, 2022). "To assess the clinical relevance of targeting the SSP in CRC for radiosensitizing purposes, we first examined mRNA levels of PHGDH, PSAT1 and PSPH in patient-derived data from normal tissues (TCGA Target GTEx) and CRC tumor tissues (TCGA COAD study) using the online Xena Explorer tool." (PMID 36291844, 2022). "These cells are not able to upregulate crucial genes from the serine biosynthesis pathway (SBP), such as phosphoglycerate dehydrogenase (PHGDH) and phosphoserine aminotransferase 1 (PSAT1), making them dependent on serine released by tumour-infiltrating nerves to the microenvironment." (PMID 34588983, 2021). "Because PHGDH is the first rate-limiting key metabolic enzyme in the SGOC pathway, PHGDH inhibition may create a metabolic vulnerability in tumours with a highly activated SGOC metabolism." (PMID 32034121, 2020). "Expression of PHGDH, PSAT1, PSPH and tumor SHMT1 is higher in PDTC and PTC, but lower in MTC." (PMID 31423225, 2019). "Therefore, we next performed dual immunofluorescence staining to determine the paired expression of PHGDH and PSAT, or PHGDH and PSPH in tumor cell monolayers." (PMID 29925909, 2018). "The other PHGDH shRNA did not inhibit tumor growth significantly, although robust PHGDH knockdown was achieved." (PMID 24318446, 2013). "However, like PHGDH, PKM2 is shown to be dispensable for tumor maintenance and growth in xenograft mouse models." (PMID 24318446, 2013). "We found that PHGDH expression levels correlated with the tumor grade, whereas normal brains showed no detectable PHGDH staining." (PMID 23229761, 2013). "Serine dehydratase and serine aminotransferase activities were absent, whereas 3-phosphoglycerate dehydrogenase and serine hydroxymethyltransferase activities were markedly increased in both tumour types." (PMID 3126791, 1988). "PHGDH functions as a multidimensional signaling hub where non-canonical activities and tissue-specific dependencies converge through spatially organized interactomes and PTMs, driving context-dependent tumor progression, stemness, and therapy resistance." (PMID 41486146, 2026). "Moreover, PHGDH, as the first key enzyme in SSP, is overexpressed in both TNBC and BLBC, partly due to copy number amplification, and its catalytic activity is crucial for tumor proliferation." (PMID 39973065, 2025). "A similar pattern was observed in KRAS‐stratified analysis: PHGDH was positively correlated with proliferative pathways in both KRAS‐mutant and wild‐type groups, while it showed a negative correlation with inflammation‐related pathways specifically in KRAS wild‐type tumours." (PMID 40660426, 2025). "When ADH1C overexpressed, suppresses the expression of Phosphoglycerate Dehydrogenase (PHGDH) and Phosphoserine Aminotransferase 1 (PSAT1), two key enzymes in the serine biosynthetic pathway, leading to lower intracellular serine levels and reduced tumor growth." (PMID 40951358, 2025). "Moreover, real‐world cohort analysis revealed that PHGDH was significantly overexpressed in both primary CRC and liver metastases, and its expression positively correlated with the Ki67 index, tumour size and N stage, suggesting its potential role as a key metabolic driver in CRC progression." (PMID 40660426, 2025).
tumor (continued). "Moreover, the suppression of PHGDH or PSAT1 significantly decreased the conversion of glutamate to αKG and decreased the cellular αKG pool in protumorigenic macrophages and in the serum of tumor-bearing mice." (PMID 38409249, 2024). "We previously demonstrated that PHGDH and PSPH catalyze the conversion of 3- phosphoglycerate to serine, leading us to assess Phgdh and Psph mRNA and protein levels in LK, B lymphocytes, plasma cells, T lymphocytes, erythroid cells, and BMSCs isolated from the BM of tumor-bearing 5TGM1 mice." (PMID 37055385, 2023). "Of interest, six proteins (FOXA1, ERBB2, MAPT, NAT1, PHGDH, KRT5) and one protein (PHGDH) overlapped between PAM50 and the differentially expressed proteins between basal-like and luminal-like subtypes in microdissected tumor epithelium and stroma, respectively." (PMID 37349288, 2023). "In addition, PHGDH inhibitor, NCT‐503, was shown to impede tumor growth in vivo effectively." (PMID 37387559, 2023). "Moreover, 3-phosphoglycerate dehydrogenase (PHGDH), which interconverts 3-phosphoglycerate (3-PG) to 3-phosphohydroxypyruvate (3-PHP) during serine biosynthesis, was recently reported to sustain tumor growth upon glucose restriction." (PMID 36476366, 2022). "In the same vein, PHGDH inhibition is not always sufficient to inhibit tumor growth." (PMID 31980738, 2020). "Interestingly, in this study, inhibiting PHGDH attenuated metastasis without affecting extra-cranial tumour growth, suggesting that the consequences of increased PHGDH expression were directly related to upregulated metastasis." (PMID 33511334, 2020). "However, inhibition of PHGDH is not always sufficient to inhibit tumor growth, in part because serine is readily available in human plasma and can be taken up to compensate for a loss of serine biosynthesis." (PMID 31096630, 2019). "Despite limitations to this approach, we have identified several single agents that are highly cytotoxic to EFT cells, and morpholino cocktails targeting PHGDH transcripts, in combination with XAGE1 or CYP4F22, may be highly synergistic across multiple EFT tumor types." (PMID 30093970, 2018). "Both PHGDH and PSAT1 contribute to serine/ glycine biosynthesis, which plays an important role in supporting nucleotide synthesis in rapidly proliferating cells, and recent publications indicate that high expression of PHGDH in tumor tissue is required for cell growth in epithelial malignancies." (PMID 26499495, 2015). "PHGDH inducible knockdown was started at relative smaller tumor size in both MCF10DCIS.com and MDA-MB-468 in vivo models, which may be more relevant to the tumor initiation status." (PMID 24318446, 2013). "That study demonstrated that genetic suppression and pharmacologic inhibition of PHGDH using PH‐719 or PH‐755 reduced brain metastases in vivo, but not extracranial tumor growth, implying that PHGDH inhibitors could be clinically effective for treating brain metastases." (PMID 40552664, 2025). "In addition to synthesizing serine, PHGDH may also promote tumour proliferation in noncanonical ways." (PMID 38577610, 2024). "Thus our results further support the involvement of PHGDH in ER negative tumours." (PMID 26725330, 2016). "PKUMDL – and PKUMDLWQ WQ - 2101-2201 in vivo selectively inhibit PHGDH amplification MDA - MB - 468 transplanted tumor, without affecting the MDA - MB231 transplantation tumor growth." (PMID 40265021, 2025). "We treated B16F10 tumor-bearing mice with or without NCT503, an inhibitor of the serine synthase PHGDH to inhibit l-serine synthesis, and with the anti-PD1 mAb." (PMID 37223471, 2023). "Unlike PHGDH, PSAT1 overexpression has not been found in TNBC tumor cells, and PSAT1 upregulation is generally presumed to result from responses to oncogenic signals." (PMID 32296646, 2020).
tumor (continued). "Similar to the MDA-MB-468 xenograft mouse model, PHGDH shRNA also did not inhibit tumor growth significantly in HCC1806 and BT-20 xenograft mouse models, although robust PHGDH knockdown was also achieved in either the mRNA or protein level." (PMID 24318446, 2013). "However, a study from Novartis showed that knockdown of PHGDH in two TNBC cell lines, HCC1806 and BT-20, did not affect tumor growth in xenograft models." (PMID 37444501, 2023). "Similarly to PHGDH disruption, we found that PSAT1 knockout did not affect the tumor growth in vivo (right)." (PMID 32138178, 2020).
infection (23 papers, 2009 to 2025). The state of being infected such as from the introduction of a foreign agent such as serum, vaccine, antigenic substance or organism. "The differential gene expression observed at day 15 post-infection demonstrated a consistent pattern of gene up regulation of PHGDH and PSAT1 and down regulation of APOC1, FADS2, FXYD2, KIAA0125, and MMP12 over a period of time in HIV-1 infected PBMC." (PMID 26821323, 2016). "Furthermore, soft clustering analysis and LASSO/Cox machine learning methods were employed to successfully analyze the changes in expression profiles across various infection time points, leading to the identification of two important genes, PHGDH and NLRP12." (PMID 38257759, 2023). "Further review of the literature uncovers the extensive research significance and value of PHGDH and NLRP12 in virus-infection-related studies." (PMID 38257759, 2023). "The results indicated that CSFV infection led to a decrease in PHGDH protein expression levels at 24 and 48 h post-infection in both PK-15 and 3D4/2 cells, while there was no significant impact on PHGDH mRNA transcription levels." (PMID 39207107, 2024). "In glycine, serine, and threonine metabolism, the expression of PHGDH, phosphoserine aminotransferase (PSAT) and PSPH, which converted the glycolytic intermediate 3-phosphoglycerate (3-PG) to serine, were activated after infection." (PMID 37358285, 2023). "PCK1 increased H3K9me3 levels, while targeting PHGDH by sgPHGDH or inhibitor NCT503 after AdPCK1 infection failed to enhance H3K9me3 levels." (PMID 37166978, 2023). "PHGDH and PSPH also increased their expression due to infection with the cp strain." (PMID 35746747, 2022). "Interestingly, within these intersections, two genes, PHGDH and NLRP12, consistently appeared at all time points, and their expression trends remained largely consistent across various infection time points." (PMID 38257759, 2023).
neurological disease (6 papers, 2018 to 2025). "This study reveals the role and mechanism of PHGDH-mediated serine synthesis in promoting the inflammatory response of astrocytes which may provide a potential target for neurological diseases involving neuroinflammation." (PMID 40383841, 2025). "Serine is well-known to be a neurotransmitter and PHGDH KO mice exhibited neurological disorder and could not survive long after birth." (PMID 31615983, 2019).
metabolic disease (4 papers, 2021 to 2025). A congenital disorder (due to inherited enzyme abnormality) or acquired (due to failure of a metabolically important organ) disorder resulting from an abnormal metabolic process. "Our study provides a framework for elucidating the exact mechanism whereby PHGDH contributes to longevity, and paves the way for designing tissue-specific interventions, aiming to alleviate metabolic disease-associated pathology." (PMID 35115503, 2022).
mitochondrial disease (1 paper, 2025). "PHGDH, a key enzyme in serine biosynthesis and one-carbon metabolism, is frequently upregulated in mitochondrial disease models." (PMID 40750944, 2025).
PHGDH also shares sentences with these, for which no sentence is quoted: astrocytic tumor (3 papers); adenocarcinoma (2); brain tumor (2); brucellosis (2); chronic lymphocytic leukemia (2); head and neck cancer (2); Hyperglycemia (2); Parkinson disease (2); renal cell carcinoma (2); type 2 diabetes (2); abortion (1); adrenal tumors (1); alcohol abuse (1); alcoholic hepatitis (1); anaplastic astrocytoma (1); Arthritis (1); asthma (1); atherosclerosis (1); autoimmune disease (1); bacterial infection (1); Beckwith-Wiedemann syndrome (1); bone metastasis (1); brain cancer (1); Candida infection (1); cardiac hypertrophy (1); cardiovascular disease (1); carnosinase deficiency (1); Cerebral ischemia (1); cervix (1); chondrosarcoma (1).
A further 56 diseases each share a sentence with PHGDH in 1 paper.